TSKS (testis specific serine kinase substrate)
Description:
May play a role in testicular physiology, most probably in the process of spermatogenesis or spermatid development.
Synonyms: STK22S1; TSKS1; TSSKS; PPP1R161
Tractability: No criterion of Open Targets' tractability assessment is met for any kind of drug.
Gene: Protein-coding gene on chromosome 19 (49,739,753 to 49,763,306, reverse strand). Ensembl gene ENSG00000126467.
Subcellular location: Cytoplasm, cytoskeleton, microtubule organizing center, centrosome, centriole
Gene Ontology:
Molecular function: protein binding; protein kinase binding
Cellular component: centriole
Genetic constraint (gnomAD): Loss-of-function variants: 25 observed, 59.48 expected, observed/expected ratio (o/e) 0.42, 90% interval 0.31 to 0.59. The upper end of that interval is the gene's LOEUF score, 0.59, which puts it in group 2 of 6, group 1 being the genes least tolerant of losing a copy. Missense variants: 777 observed, 766.33 expected, observed/expected ratio (o/e) 1.01, 90% interval 0.95 to 1.08. Synonymous variants: 325 observed, 334.75 expected, observed/expected ratio (o/e) 0.97, 90% interval 0.89 to 1.06.
Homologues: Orthologues: chimpanzee TSKS (96% identical), macaque TSKS (95% identical), dog TSKS (84% identical), pig TSKS (84% identical), mouse Tsks (83% identical), rat Tsks (77% identical), guinea pig TSKS (76% identical), rabbit TSKS (70% identical).
Diseases named in the same sentence as TSKS in open-access papers:
TSKS is named in the same sentence as 4 diseases in open-access papers, as found by Europe PMC text mining. Sharing a sentence is not in itself a finding about the gene and the disease. The quoted sentences say what the papers report.
tumor (6 papers, 2021 to 2024). "These TSKs were shown to express epithelial-mesenchymal transition markers and to reside within a fibrovascular niche at leading edges of the tumor." (PMID 33497366, 2021). "Furthermore, Mmp10-positive TSKs correlated with G2/M clusters, suggesting that they reside in proliferative tumour areas." (PMID 39020166, 2024). "During progression through normal-AK-SCC-Metastasis, we found a significant reduction in the proportion of Normal Keratinocyte Differentiated cells (NKD) and an increase in the proportion of TSKs and the appearance of a Tumour Keratinocyte Differentiated population (TKD) at the AK stage." (PMID 37626054, 2023). "Importantly, it was largely downregulated in a subset of TSKs that resides at the leading edges of the tumor in a fibrovascular niche." (PMID 33497366, 2021). "Besides, the subpopulation of TSKs in their study only accounted for 2.7–13.8% of all tumor cells." (PMID 38099574, 2023). "Mmp10-positive TSKs more closely resembled the human TSK signature and resided at the invasive front, forming invading nests and marking invasive fronts at the tumour base." (PMID 39020166, 2024).
cancer (1 paper, 2022). A tumor composed of atypical neoplastic, often pleomorphic cells that invade other tissues. "By comparing their differentially expressed genes, EMT-like TSKs were dramatically enriched with ECM organization, proteoglycans in cancer, regulation of cell adhesion, and the VEGFA-VEGFR2 signaling pathway, representing more invasive properties compared with EMT-unlike TSKs." (PMID 35908020, 2022).
TSKS also shares sentences with these, for which no sentence is quoted: male infertility (3 papers); Infertility (1).